INS (insulin)
Diseases named in the same sentence as INS in open-access papers (continued):
Sharing a sentence is not in itself a finding about the gene and the disease.
Hypoglycemia (continued). "One participant experienced nocturnal asymptomatic severe hypoglycemia during the first evaluation period, when under treatment with a DPP-4 inhibitor and insulin degludec, but this did not recur after switching to IDegLira, without a change in the insulin dose." (PMID 35097130, 2022). "While insulin-induced hypoglycemia did not alter plasma VEGF levels in either control or T2D subjects, plasma SEMA3A levels significantly decreased at hypoglycemia in control cases compared to baseline (799 ± 27 vs 935 ± 45 RFU of SEMA3A in control, hypoglycemia vs baseline, p=0.01)." (PMID 34248841, 2021). "Moreover, when insulin and glucagon levels were combined in the IGR, lower IGR was observed in the group without hypoglycemia, suggesting a catabolic status with increased hepatic glucose output and further stressing hypothesis." (PMID 33424773, 2020). "There are no randomized trials evaluating the use of insulin for the long-term management of PLTDM compared to other antidiabetic therapies, but a rational conduct is to continue insulin therapy in patients who are discharged with good glycemic control and no hypoglycemia." (PMID 29411291, 2018). "Of note are the observations that linagliptin significantly improved hypoglycemia in klotho−/− mice, as shown by the findings of OGTT and significantly increased non-fasting blood glucose levels, while linagliptin did not affect serum insulin levels of klotho−/− mice." (PMID 29195509, 2017). "Additionally, previous studies have indicated that add-on therapy of sitagliptin to various insulin regimens (not including CSII) could decrease daily insulin doses and improve glycemic control without severe hypoglycemia or weight gain." (PMID 26798658, 2016). "In a recent study, our group showed that, although insulin was able to protect type 1 diabetic STZ rats (either exposed or not to Aβ) against brain oxidative stress and mitochondrial dysfunction, this was not the case in STZ rat brain after an acute hypoglycemia episode." (PMID 22500228, 2012). "Similarly to inTandem1, there was a significant reduction in HbA1c, weight, fasting glucose and insulin doses, with a 24‐week continuous glucose monitoring (CGM) sub‐study showing increased time in range and decreased postprandial excursions in glucose without an increase in hypoglycaemia." (PMID 40130476, 2025). "Our results indicate that velagliflozin, whether used in combination with insulin or as monotherapy, significantly improves glycemic control as reflected by reductions in MG, increases in TIR%, and decreases in TAR%, without increasing TBR% or inducing clinical hypoglycemia." (PMID 40853201, 2025).
metabolic syndrome (4,645 papers, 2002 to 2026). A cluster of metabolic risk factors for CARDIOVASCULAR DISEASES and TYPE 2 DIABETES MELLITUS. "Dyslipidemia can result from insulin deficiency or resistance, as insulin inhibits HMG‐CoA reductase, a key enzyme that regulates cholesterol‐rich LDL particle metabolism." (PMID 41583543, 2026). "IR, characterized by diminished insulin responsiveness in peripheral tissues, is central to metabolic syndrome and is intricately associated with disorders such as type 2 DM and numerous cardiovascular diseases." (PMID 41481639, 2026). "Hepatic insulin clearance has a profound effect on serum insulin levels and glucose homeostasis, and decreased insulin clearance is implicated in the development of hyperinsulinemia in metabolic syndrome." (PMID 40522859, 2025). "In the quercetin group, insulin and blood glucose levels were significantly improved; the risk of metabolic syndrome was reduced in animal models." (PMID 41427055, 2025). "High-intensity interval training decreases RBP4 levels and improves insulin sensitivity in metabolic syndrome, and weight loss through bariatric surgery also reduces RBP4 levels and improves metabolic outcomes." (PMID 40276651, 2025). "The methylation of FABP3 is associated with insulin, lipids, and cardiovascular phenotypes of the metabolic syndrome." (PMID 41019337, 2025). "IR refers to the decreased efficiency of insulin in facilitating glucose uptake and utilization, serving as a prominent feature of metabolic syndrome and is recognized as one of the critical risk factors for IS." (PMID 40520776, 2025). "These pathways are critical for glucose uptake and insulin-mediated cellular responses, and their dysregulation is associated with IR and metabolic syndrome." (PMID 40255834, 2025). "Turkish cuisine, particularly in coastal regions, incorporates more olive oil (rich in monounsaturated fats) compared to Iran’s reliance on hydrogenated oils and animal fats, which are linked to dyslipidemia and insulin resistance." (PMID 41401167, 2025). "Reduced insulin requirements are the most common and durable effect; however, variability in glycemic responses and potential risks (HypoG, dyslipidemia, micronutrient deficiencies) require individual monitoring." (PMID 41228423, 2025). "These surgical procedures facilitate weight loss and improve insulin sensitivity, body glucose control, dyslipidemias, and hypertension." (PMID 41191655, 2025). "DCA has been linked to several harmful effects at the cellular level, including inflammation and immune dysregulation and risk factors for dyslipidemia and reduced insulin sensitivity." (PMID 40559388, 2025). "A low‐fat diet likely exerts its beneficial effect via weight loss and concomitant improved insulin sensitivity, instead of lowering cholesterol levels, based on our multivariable analysis of metabolic syndrome constituents (model B)." (PMID 40302139, 2025). "Results from studies show that people who have a higher BMI need larger insulin doses because their insulin sensitivity decreases, which leads to complicated treatment, along with elevated metabolic syndrome and cardiovascular risk." (PMID 40225541, 2025). "Insulin serves as a central regulator of metabolic homeostasis, and dysregulation of insulin secretion and action is closely linked to modern sedentary lifestyles, overnutrition, and metabolic syndrome, which are key contributors to T2D development." (PMID 41346675, 2025). "Conversely, female sex, the presence of dyslipidemia, and concurrent use of statins, insulin, and SU were associated with high GLP1RA utilization." (PMID 40589143, 2025). "Rationally, it looked at variables associated with metabolic syndrome including body weight/BMI, waist circumference, glucose/insulin level changes, and lipid profile." (PMID 40998755, 2025).
metabolic syndrome (continued). "Epidemiological evidence suggests that diets rich in flavonoid-containing foods are associated with reduced risk of metabolic syndrome, improved insulin sensitivity, and better cardiovascular health, outcomes directly relevant to PCOS." (PMID 41155686, 2025). "Sweetened beverages raise blood glucose, insulin, triglycerides, and inflammatory markers, contributing to metabolic syndrome and cardiovascular risk, with studies linking high-sugar sweetened beverage consumption to 19% higher MI risk (RR 1.19)." (PMID 40431346, 2025). "The GO analysis in the present study also indicates the role of associated genes with risk factors of T2D based on their role in regulating dyslipidemia, insulin transport, MAPK pathway, glucose homeostasis, and many more." (PMID 39747296, 2025). "Beyond the standard liver-targeted outcomes such as steatosis, transaminase and fibrosis rates, trials should also include assessment of improvements in insulin resistance, dyslipidemia, blood pressure management and cardiovascular risk." (PMID 39860434, 2025). "This comprehensive review has highlighted polydatin’s multifaceted roles in enhancing insulin sensitivity, improving pancreatic function, and mitigating the risk of metabolic syndrome." (PMID 40958722, 2025). "Visceral and abdominal adipose tissue, in particular, negatively impacts metabolic and insulin signaling pathways, contributing to the pathogenesis of obesity and other metabolic syndrome risk factors." (PMID 40077747, 2025). "Children with vitamin D deficiency are more likely to exhibit impaired glucose tolerance, higher fasting insulin levels, and increased risk for metabolic syndrome." (PMID 41362334, 2025). "This dietary disruption not only directly disrupts insulin secretion rhythms but also further exacerbates cortisol imbalance, significantly increasing the risk of metabolic syndrome." (PMID 41415241, 2025). "Elevated triglyceride levels, a hallmark of metabolic syndrome, are linked to impaired insulin signaling and pancreatic β-cell dysfunction, both of which play critical roles in the pathogenesis of diabetes." (PMID 40594785, 2025). "Multiple studies confirm its strong correlation with clamp-measured insulin sensitivity and its superior diagnostic accuracy for metabolic syndrome compared to HOMA-IR, as evidenced by a significantly larger area under the ROC curve." (PMID 40703260, 2025). "These parameters are not only diagnostic markers of metabolic syndrome but also contribute to the pathophysiologicaldevelopment of hepatic fat accumulation through mechanisms involving insulin resistance, lipotoxicity and chronic low-grade inflammation." (PMID 41393463, 2025). "In the present study, mice fed a ketogenic diet had higher blood ketone concentrations and lower blood glucose and insulin concentrations than those administered a liquid diet, but ketogenic diets also caused dyslipidemia." (PMID 40806013, 2025). "Visceral obesity is linked to resistance to insulin actions and high levels of insulin, as well as issues like dyslipidemia, T2DM, hypertension, and increased risk for CVD." (PMID 41441018, 2025). "Key risk factors, collectively referred to as metabolic syndrome, include dyslipidemia, leptin and adiponectin dysregulation, insulin resistance, impaired insulin secretion, and glucose intolerance." (PMID 41220421, 2025). "These taxa are highly discriminant for type 2 diabetes (T2D) and have been linked to improved insulin sensitivity and fecal microbiota transplantations from lean donors to recipients with metabolic syndrome improved insulin sensitivity." (PMID 40313602, 2025). "This study demonstrates that seasonal variation in PM2.5 exposure is associated with significant changes in insulin and leptin levels, with more pronounced responses among individuals with metabolic syndrome." (PMID 40863890, 2025).
metabolic syndrome (continued). "VAV2 deficiency in mice led to reduced muscle mass, insulin responsiveness, and ultimately symptoms resembling metabolic syndrome." (PMID 40813973, 2025). "Preservatives in processed meats, such as nitrates and nitrites, are associated with endothelial dysfunction and impaired insulin responses, and consumption of processed meats increase the risk of hypercholesterolemia, hypertriglyceridemia, and dyslipidemia." (PMID 39713783, 2024). "PC (33:2) and PC (33:1) exhibited higher concentrations in subjects with Metabolic Syndrome, showing associations with triglycerides and waist circumference and positive correlations with insulin and HOMA-IR." (PMID 38932852, 2024). "Of note, the waist-height ratio which is a marker of central fatness and is linked to insulin sensitivity, performed similar to the presence of the metabolic syndrome for the prediction of CAD in the entire cohort and in all KDIGO categories." (PMID 38702680, 2024). "Being overweight or obese is a significant risk factor for metabolic syndrome, a condition characterized by chronically elevated levels of circulating insulin." (PMID 39286267, 2024). "The 20-HETE GPR75 axis has been implicated in cardiovascular, metabolic syndrome, and cancer through its vasoconstriction, insulin resistance, and proliferative properties." (PMID 39959811, 2024). "Carvalho and colleagues, by studying a group of young adult obese patients, associated high GDF-8 and LP/ADP levels with metabolic syndrome, glucose-insulin homeostasis impairment, and low muscle mass." (PMID 39407757, 2024). "Accumulation of fat predominantly inside the abdominal cavity relative to abdominal subcutaneous depots has been strongly linked to metabolic syndrome, potentially due to differences in immune and endocrine functions, insulin sensitivity and lipid metabolism." (PMID 39401200, 2024). "BPA exposure has been linked to metabolic syndrome by interfering with lipid metabolism and insulin signaling, potentially through miRNA-mediated pathways that affect PTEN and other regulatory genes." (PMID 39298504, 2024). "One recent study reported that MetS was associated with a greater risk of 1-year MACCE in patients undergoing PCI18, this risk was related to hypertension, dyslipidemia, and insulin-treated diabetes." (PMID 38184738, 2024). "The hypothalamic–pituitary–adrenal and somatotropic axes activities are temporally associated with delta power sleep and promote insulin sensitivity and metabolic syndrome." (PMID 38956202, 2024). "Atp10A deficient mice display female-specific diet-induced dyslipidemia, broad changes to lipid metabolism, and disruptions in liver insulin signaling." (PMID 38172157, 2024). "Specific genetic variations can influence fat distribution, insulin sensitivity, and lipid metabolism, making individuals more susceptible to metabolic syndrome." (PMID 39574946, 2024). "Specifically, suppression of slow-wave sleep has been shown to impair insulin sensitivity, causing impaired glucose tolerance and a greater risk of metabolic syndrome." (PMID 38540695, 2024). "Flavonoids, recognized for their antioxidant effects, have been linked to enhancing insulin sensitivity and decreasing inflammation, which are crucial elements in the development of metabolic syndrome." (PMID 38794679, 2024). "Residents with excessive waistline are at increased risk of dyslipidemia due to excessive accumulation of abdominal fat, resulting in increased insulin resistance, decreased lipoprotein lipase activity, and increased TG and TC proteolipase activity." (PMID 39678246, 2024). "Reduced SOD activity is suggested to be associated with metabolic syndrome as well as impaired insulin sensitivity and β-cell dysfunction." (PMID 39596317, 2024). "Paternal high-fat diets, along with other unbalanced diets, have been found to raise the risk of metabolic syndrome in offspring, mainly through epigenetic changes in genes that regulate metabolism and insulin sensitivity." (PMID 39770898, 2024).
metabolic syndrome (continued). "PCOS patients are at risk of cardiac diseases, metabolic syndromes, resistance to insulin, infertility, and many more." (PMID 38779261, 2024). "The post hoc analysis found that tirzepatide at all doses investigated reduced the prevalence of metabolic syndrome related to cardiovascular risk factors more than placebo, semaglutide 1 mg, insulin degludec, and insulin glargine." (PMID 38987789, 2024). "ADM helps improve vascular function, reduce hypertension, and promote insulin sensitivity—all factors that reduce the risk of metabolic syndrome and cardiovascular disease." (PMID 39335642, 2024). "It was first observed that the level of E. hallii (formal nomenclature of A. soehngenii) in the small intestine was associated with improved insulin sensitivity after an FMT from lean subjects to those with metabolic syndrome." (PMID 39064765, 2024). "A gradual decrease in insulin sensitivity during the progression of metabolic syndrome/PreDM and T2DM in monkeys was associated with the decreases in amylase and increases in lipase." (PMID 38955666, 2024). "Higher intake has a positive effect on improving insulin sensitivity, modulating the secretion of certain gut hormones and influencing various metabolic and inflammatory markers associated with the metabolic syndrome." (PMID 39519410, 2024). "Regular physical activity helps maintain a healthy weight, improves insulin sensitivity, and reduces the risk of metabolic syndrome." (PMID 39310549, 2024). "The severity of metabolic syndrome is correlated to the reduction in hepatic insulin clearance, and, furthermore, insulin has been linked with acting as an anti-inflammatory and proinflammatory agent." (PMID 38397999, 2024). "HFD causes rats to become obese and develop dyslipidemia, which in turn leads to increased insulin secretion." (PMID 39758340, 2024). "FABP3's function is also associated with inflammatory conditions, insulin sensitivity, and metabolic syndrome." (PMID 38440405, 2024). "Maternal overnutrition can lead to excessive fetal nutrient exposure, resulting in altered pancreatic development, impaired insulin sensitivity, and an increased risk of metabolic syndrome in later life." (PMID 39770898, 2024). "Another study showed that transplantation of fecal microbiota from lean donors to individuals with metabolic syndrome caused improved insulin sensitivity in the recipients." (PMID 37009872, 2023). "Metformin has a key role in hepatic glucose production and insulin sensitivity that should help in NAFLD associated with metabolic syndrome." (PMID 36940044, 2023). "This type of dyslipidemia is primarily caused by impaired insulin sensitivity in the liver and adipose tissue." (PMID 38125279, 2023). "These phenotypes, like those of other animal models of metabolic syndrome, were associated with impaired insulin secretory responses to exogenous glucose or fasting/refeeding cycles." (PMID 37819196, 2023). "IR is a state of reduced sensitivity and impaired response to insulin action, which has been identified as a pathogenic driver of DM and metabolic syndrome." (PMID 37865782, 2023). "The metabolic alterations observed in the offspring with hypertensive parents, such as increased serum insulin level, IR, and dyslipidemia, have been associated with increased sympathetic activity." (PMID 37799258, 2023). "Accumulation of hepatic triacylglycerol (TG) is highly associated with impaired whole-body insulin-glucose homeostasis and dyslipidemia." (PMID 37591342, 2023). "Consistently, garlic improves insulin sensitivity and the associated metabolic syndrome in animal models, and its derivatives reduce both insulin resistance and blood glucose in streptozotocin- and alloxan-induced diabetes." (PMID 37569263, 2023). "Dysregulation of its interaction with GH and insulin can lead to metabolic syndrome including IR, which increases the risk of T2DM up to fivefold." (PMID 38018587, 2023).